PPARGC1A (PPARG coactivator 1 alpha)
Diseases named in the same sentence as PPARGC1A in open-access papers (continued):
Sharing a sentence is not in itself a finding about the gene and the disease.
Obesity (continued). "Expression of Ppargc1a is reduced in insulin resistant tissues, during obesity and in type 2 diabetes; and Ppargc1a knock-out mice exhibit hepatic steatosis due to a reduction in mitochondrial oxidative capacity and mtDNA content, together with an upregulation of lipogenic gene expression." (PMID 23783067, 2013). "The link between PPARGC1A gene and fat oxidative metabolism suggest that this gene may influence athletic performance on one hand, and prevention of obesity on the other hand." (PMID 23573268, 2013). "Our results provide some support for the involvement of the PPARGC1A Gly482Ser SNP in body weight or the pathophysiology of obesity related phenotypes in Pacific populations, but large-scale GWA studies in Pacific populations are desired to test this association more robustly." (PMID 21244673, 2011). "Although beyond the scope of this study, additional experiments involving whole genome methylation profiling, or assessment of methylation of genes such as PPARGC1A, IGFBP-1, and SLC6A4, which have previously been shown to be associated with T2D and obesity, may be beneficial." (PMID 34485290, 2021). "Likewise, the other two DEGs identified in the present study—PPARGC1A (peroxisome proliferator-activated receptor-γ co-activator-1alpha) and PCSK1N (proprotein convertase subtilisin/kexin type 1 inhibitor)—have been associated with obesity in humans." (PMID 32485856, 2020). "When the phenotypes of high-fat diet-induced obese (DIO) mice were compared with high-fat diet-induced obesity-resistant (DIO-R) mice, the DIO-R mice had significantly higher levels of AMPK activation, as well as PPARGC1A and ESRRA expression." (PMID 32121253, 2020). "In this context, it has been shown that obesity is due mainly to an increase in adiposity, where many functional genes are altered; among them are PPARG2 and its coactivator PPARGC1A." (PMID 26185753, 2015). "Moreover, adipose-specific FLCN null mice exhibit increased energy expenditure and protection from high-fat diet (HFD)-induced obesity through the chronic hyperactivation of AMPK, showing activation of the PPARGC1A-ESRRA axis in adipose tissue." (PMID 32121253, 2020). "Similarly, increasing the expression of peroxisome proliferator-activated receptor gamma coactivator 1 alpha (PPARGC1A), the protein ligand of ESRRA, increases energy expenditure and reduces obesity." (PMID 32121253, 2020). "The down-regulated expression of GCK and up-regulated expression of IGFBP1, PPARGC1A and SLC2A4 may indicate obesity and insulin resistance in rhesus models of liver steatosis." (PMID 26442469, 2015). "The network shows that RXRA interacts with proteins related to a tumor (THRA related to pituitary adenome) and those related to certain diseases caused by abnormalities in lipid metabolism (e.g., NR0B2 related to obesity, PPARA to hyperapobetalipoproteinemia, and PPARGC1A to lipodystrophy)." (PMID 17705877, 2007). "Using peripheral blood mononuclear cells as a source of DNA, another epigenome-wide study compared insulin-resistant versus insulin-sensitive non-diabetic women with obesity, classified according to hyperinsulinemic euglycemic clamps, without finding differences by PPARGC1A methylation status." (PMID 32933059, 2020). "UCP1, PPARG coactivator 1 alpha (PPARGC1A), transcription factor A, mitochondrial (TFAM), T-box transcription factor 1 (TBX1), and solute carrier family 27 member 1 (SLC27A1) expression was assayed in SAT and VAT samples, obtained during sleeve gastrectomy from 62 patients with obesity." (PMID 31440209, 2019). "Overall, our results support that PPARGC1α DNA methylation is responsive to metabolic variations related to glucose homeostasis during pregnancy, which might affect BAT activation and the development of obesity." (PMID 27340502, 2016).
Obesity (continued). "Ppargc1a plays an important role linking thermogenesis to risk of T2D as illustrated by genetic ablation studies of Ppargc1a in mice, after which thermogenesis was impaired and susceptibility to HFD-induced insulin resistance, but not obesity, was increased." (PMID 25076055, 2014).
Insulin resistance (343 papers, 2008 to 2026). Increased resistance towards insulin, that is, diminished effectiveness of insulin in reducing blood glucose levels. "Observational studies have also linked the T allele or decreased PPARGC1A expression with insulin resistance or excess adiposity in adults and children of varying ethnicities." (PMID 37171500, 2023). "Subjects who had the reference allele in PPARGC1A and the variant allele of PPARγ exhibited higher fasting insulin levels, insulin resistance, and insulin area under the curve compared to those with the other combinations." (PMID 37513946, 2023). "Previously, PPARGC1A gene rs8192678 polymorphism has been associated with a subcutaneous adiposity accumulation and with insulin resistance in obese adults." (PMID 35936915, 2022). "In vivo, massive over-expression of PPARGC1A was associated with insulin resistance; however, a modest increase in expression, as seen with exercise, improves insulin sensitivity." (PMID 30540820, 2018). "PPARGC1A overexpression in liver has been associated with hepatic insulin resistance, manifested by higher glucose production and impaired suppression of gluconeogenesis in response to insulin in transgenic mice." (PMID 30540820, 2018). "We were unable to establish an association between PPARGC1A gene expression and in vivo insulin resistance in the total population of FDR in our study." (PMID 23505498, 2013). "Second, alocus on chromosome 4p15.1, where the PPARGC1A is located, was found to be associated with abdominal obesity and insulin resistance." (PMID 19360113, 2009). "Together with the predicted upregulation of Adipoq, Pparg and Ppargc1a and downregulation of Nos2 nodes, the overall transcriptome shift corresponds to a gene expression profile repeatedly associated with amelioration of insulin resistance." (PMID 36245490, 2022). "Collectively, these data suggested that the upregulated expression of Hk2, Ppargc1a, Sorbs1, and Hmox1 might be implicated in the improvement of hyperglycemia and insulin resistance in the exercise GK rats." (PMID 31338039, 2019). "Indeed, thermogenesis impairment and HFD-induced insulin resistance susceptibility were observed in Ppargc1a genetic ablation studies in mice." (PMID 30687113, 2018). "PGC-1α dysregulation is often associated with insulin resistance and T2D, which suggest that variations within the PPARGC1A gene may influence transcriptional homeostasis of the genes involved." (PMID 25977930, 2015). "Defect in mitochondrial oxidative phosphorylation have been linked to insulin resistance, and there is also evidence suggesting that polymorphisms in PPARGC1A are associated with an increased relative risk of type 2 diabetes, defects in insulin secretion, and lipid oxidation." (PMID 25302081, 2014). "Whatever the mechanism may be, the hypothesis that increased methylation of the PPARGC1A promoter is associated with insulin resistance seems questionable and needs further investigation." (PMID 23505498, 2013). "IRS1 and PPARGC1A belong to the small group of T2D susceptibility genes which might mediate their effects through insulin resistance and therefore be relevant in peripheral tissues such as SAT and skeletal muscle." (PMID 23251491, 2012). "As increased hepatosteatosis was shown to correlate with reduced Ppargc1α expression, it can be speculated that lower Ppargc1α levels in the liver of B6-Tg(Zfp69) mice participate in ectopic fat storage and subsequently cause insulin resistance." (PMID 26232096, 2015). "Functional enrichment analysis showed that SOCS3, IL6, FOXO1, CEBPB, SOX9, and PPARGC1A were mainly involved in the adipocytokine signaling pathway, insulin resistance, FoxO signaling pathway, AMPK signaling pathway, and PI3K-Akt signaling pathway." (PMID 38415055, 2024).
Insulin resistance (continued). "We observed a significant main effect of insulin resistance in the suppression of Ppargc1a expression, which showed pairwise difference between insulin-resistant cells and insulin-sensitive cells at 20 mM BCAA." (PMID 39057712, 2024). "We also observed a significant interaction effect between BCAA and insulin resistance, which revealed suppressed Ppargc1a expression in insulin-resistant cells treated with 20 mM BCAA versus insulin-resistant cells treated without additional BCAA." (PMID 39057712, 2024). "According to our analysis, most studies consistently reported differential DNA methylation that affected PDX-1, GLP1R, PPARGC1A, etc., and thus led to insulin resistance." (PMID 37201099, 2023). "We found that the microbiota of participants with the PPARGC1A-2 genotype was enriched in Prevotella 9, Megasphaera, Bacteroides and Lachnospiraceae UCG-007 genera, which have previously been associated with insulin resistance and diabetes." (PMID 35205333, 2022). "Microbiota analysis of subjects with PPARGC1A (rs 8192678) and PPARD (rs 2267668) SNPs revealed certain taxa associated with the development of insulin resistance and T2DM." (PMID 35205333, 2022). "Recent studies demonstrated a link between mitochondrial dysfunction and insulin resistance through altered expression of the PPARGC1A gene in muscle and liver tissue." (PMID 32528276, 2020). "In the skeletal muscle, PPARGC1A avoids the development of insulin-resistance by increasing the proportion of oxidative fibres and stimulating mitochondrial biogenesis, two features that promote fatty acid oxidation." (PMID 20540717, 2010). "Recent studies have also shown altered expression of PPARGC1A and downstream mitochondrial target pathways in the skeletal muscle of humans with insulin resistance and diabetes." (PMID 18588668, 2008). "In addition, for circFAT3 KD, genes related to insulin signaling and insulin resistance (PPARGC1A, SLC27A2, PPARGC1B, PRKCQ, GYS1, and IRS1) were the top hits." (PMID 36840844, 2023). "Thus, Gly482Ser, the most common PPARGC1A polymorphism, is associated with Type 2 DM (T2DM), but results in decreased PGC-1α mRNA levels and insulin secretion and insulin resistance." (PMID 32102312, 2020). "Additionally, different studies have proposed potential DNA methylation biomarkers in relation to plasma insulin levels, insulin secretion and insulin resistance such as those located in PPARGC1A, HTR2A, LY86, TFAM, GIPR, ADIPOQ, and IGFBP3 genes." (PMID 31208038, 2019). "In the diabetic muscle, the expression of Ppargc1a was significantly decreased, which might contribute to insulin resistance." (PMID 31338039, 2019). "The PPARGC1A rs8192678 polymorphism encodes a missense amino acid change, however, the activity of PGC-1α or genetic variations in the gene may contribute to individual variations in mitochondrial function and insulin resistance or diabetes." (PMID 25302081, 2014). "Taken together, increased DNA methylation of the PPARGC1A promoter is unlikely to play a major causal role for the development of insulin resistance in FDR of patients with T2D." (PMID 23505498, 2013). "PPARGC1A DNA methylation in the region 867-624 bp upstream from the transcription start was not affected by gender, age, BMI, fasting plasma glucose or triglyceride levels, or with insulin resistance based on the HOMA-IR index." (PMID 23505498, 2013). "Likewise, in these cancer samples, the downregulation of PPARGC1A may also contribute to downstream of insulin resistance and reduced mitochondrial fatty acid oxidation." (PMID 28886030, 2017). "Results: miR-122 was found to negatively regulate genes involved in lipid metabolism, insulin signaling, and inflammatory pathways, including PPARGC1A, PPARA, LPL, TLR4, and HMGCR, contributing to insulin resistance and liver dysfunction." (PMID 41595656, 2026).
Insulin resistance (continued). "Hyper‐ or hypomethylation of specific genes, like PPARG coactivator 1 Alpha (PPARGC1‐A), affects fatty acid β‐oxidation and correlates with insulin resistance in MASLD patients." (PMID 40693828, 2025). "In addition, by upregulating the transcription of Cpt1a, Pparα, Mcad, Acsl, and Ppargc1a, it has been demonstrated that fexaramine, an agonist of FXR, contributes to alleviating insulin resistance and lipid accumulation in NAFLD mice." (PMID 40243350, 2025). "Among these pathways, PPARGC1A, CD36, IRS2, PCK2, and IGF1 were enriched in the AMPK signaling pathway, and PCK2 was additionally enriched in the adipocytokine signaling pathway and insulin resistance." (PMID 37958518, 2023). "The degree of hepatic PPARGC1A methylation was reported to correlate with the measure of insulin resistance, HOMA-IR3, and plasma fasting insulin across NAFLD-affected and healthy individuals, and PPARGC1A was markedly hypermethylated in the livers of NAFLD patients." (PMID 34046015, 2021). "Whether the reduced Ppargc1a expression in BAT of DDT-exposed mice accounts for their reduced thermogenesis and insulin resistance needs further study." (PMID 25076055, 2014). "Collectively, the present study together with previous studies suggests that the expected inverse relationship between skeletal muscle PPARGC1A gene expression and insulin resistance or T2D is not a consistent and reproducible finding." (PMID 23505498, 2013).
diabetes (290 papers, 2008 to 2026). "PPARGC1B (peroxisome proliferator-activated receptor gamma coactivator 1-beta) is a coactivator of PPARs associated with diabetes mellitus and type 2 diabetes mellitus, whose important paralog of this gene is PPARGC1A." (PMID 41559682, 2026). "We evaluated pre-diabetes associated microRNA hsa-miR-193b-3p predicted target PPARGC1A (PGC1α), hepatic lipid content and direct or indirect effects on expression of genes regulating cellular energy metabolism, in human hepatocyte-derived cells." (PMID 36835287, 2023). "In one study, Lai and colleagues investigated the association among the PPARGC1A variations, including Gly482Ser, with DNA damage, diabetes, and cardiovascular diseases." (PMID 34394332, 2021). "The PGC-1α (encoded by Ppargc1a), whose expression is typically reduced in diabetes, is a key mediator of mitochondrial dysfunction and progression of DN." (PMID 28835257, 2017). "Further, previous studies have demonstrated the Ser allele of the PPARGC1A Gly482Ser to be associated with an increased risk of diabetes, but a recent meta-analysis have implied only a modest role for the polymorphism in the development of diabetes." (PMID 19077249, 2008). "Interestingly, we found thatthe Gly482Ser polymorphism in PPARGC1A was associated with weight gain on intensive diabetes therapy only in males." (PMID 19360113, 2009). "Due to this single-nucleotide polymorphism in PPARGC1A, it became more rigid and might disarray the structural conformation and catalytic function of the protein and might also induce type 2 diabetes mellitus (T2DM), coronary artery disease (CAD), and nonalcoholic fatty liver disease (NAFLD)." (PMID 34394332, 2021). "PPARGC1A also plays a critical role in the maintenance of glucose and energy homeostasis and is likely involved in pathological disorders such as diabetes, neurodegeneration, obesity and cardiomyopathy." (PMID 35205333, 2022). "It was published that PPARGC1A is changed in spermatozoa from patients suffering from type 2 diabetes mellitus and that increased expression of Nrf2 diminished testicular inflammation." (PMID 35909555, 2022). "In particular, PPARGC1A modulates telomere function and the DNA damage mechanism in diabetes and cardiovascular disease." (PMID 33133123, 2020). "The aim of this study is to evaluate the effect of single-nucleotide polymorphisms (SNPs) of the PPARGC1A and UCP1 genes on impaired fasting glucose (IFG) or type 2 diabetes mellitus (T2DM) and the haplotype-based interaction between these genes." (PMID 28591028, 2017). "PPARGC1A overexpression blocked diabetes-induced caspase 3 and 8 cleavage, and neuroepithelial cell apoptosis." (PMID 28474670, 2017). "Either Prkca deletion or PPARGC1A overexpression restored diabetes-suppressed autophagy and cellular homeostasis, and thus prevented NTD formation." (PMID 28474670, 2017). "Diabetes-increased number of defective mitochondria and diabetes-repressed mitochondrial gene expression were reverted by PPARGC1A overexpression." (PMID 28474670, 2017). "Rosiglitazone was shown to restore PPARGC1A expression in obese patients with type 2 diabetes mellitus." (PMID 18523557, 2008). "Although PPARGC1A is expressed at relatively low levels in the adult liver under normal conditions, its expression is markedly activated during fasting and diabetes, consistent with its role as an activator of genes involved in gluconeogenesis and fatty acid oxidation." (PMID 41465464, 2025). "Notably, the mRNA expression of Ppargc1a was lower in the kidney of mice with streptozotocin-induced diabetes, which was restored by TEPP-46 treatment." (PMID 40713487, 2025). "• Glucose uptake and TCA cycle flux decreased, mitochondria was fewer in insulin-resistant offspring skeletal muscle of diabetes history. • O-GDM had decreased PPARGC1A in skeletal muscle. • Fatty acid flux into myotube and LPL expression were lower in offspring of T2DM parents." (PMID 37255932, 2023).